OXTR (oxytocin receptor)
Diseases named in the same sentence as OXTR in open-access papers (continued):
Sharing a sentence is not in itself a finding about the gene and the disease.
neurological disease (2 papers, 2017 to 2025). "Many studies have reported that OXTR SNP rs2254298 affects various psychological dimensions and neurological diseases, such as affect, temperament, genetic variation, attachment and social cognition." (PMID 28484366, 2017).
benign tumors (1 paper, 2022). "When it comes to oxytocin, a recent study showed that benign tumors have higher expression of oxytocin receptors (OTR) than malignant tumors." (PMID 36288138, 2022).
metabolic disorder (1 paper, 2017). "If this is due to more lipid content in the KO, it will be important to test in the future if this is a precursor to the established metabolic disorder that emerges later in life for OXTR KO mice." (PMID 28235051, 2017).
reproductive system diseases (1 paper, 2023). "These early studies clearly showed that the expression of OXTR may be enhanced under specific conditions, possibly contributing to pathomechanisms of these reproductive system diseases." (PMID 36835321, 2023).
OXTR also shares sentences with these, for which no sentence is quoted: Alzheimer disease (4 papers); osteoporosis (4); atherosclerosis (3); bipolar disorder (3); breast tumours (3); attention deficit-hyperactivity disorder (2); Borderline personality disorder (2); conduct disorder (2); hyperplastic (2); metabolic syndrome (2); neurodegenerative disease (2); Sepsis (2); stress-related disorder (2); thymic lymphoma (2); acute myeloid leukemia (1); Adult onset (1); alcohol (1); allergic asthma (1); amnesia (1); Apathy (1); bladder cancer (1); breast (1); cavernous hemangioma (1); central nervous system disorder (1); cervical cancer (1); cervical incompetence (1); chronic heart failure (1); coagulation disorders (1); colorectal adenocarcinoma (1); colorectal adenoma (1).
A further 43 diseases each share a sentence with OXTR in 1 paper.